NF2 (NF2, moesin-ezrin-radixin like (MERLIN) tumor suppressor)
Diseases named in the same sentence as NF2 in open-access papers (continued):
Sharing a sentence is not in itself a finding about the gene and the disease.
neurofibromatosis type 2 (continued). "Neurofibromatosis type 2 (NF2) is a dominantly inherited autosomal disease (affecting 1 in 30,000), attributed to the loss-of-heterozygosity (LOH) of the NF2 gene." (PMID 27363027, 2016). "The tumor suppressor function of Merlin/NF2, inactivated in Neurofibromatosis type II, acts through the activation of the Hippo cascade most likely by binding and recruiting LATS to the plasma membrane, which in turn promotes LATS phosphorylation by MST." (PMID 26909043, 2016). "Clinical data was collected from five patients with type 2-neurofibromatosis (NF2) receiving anti-angiogenic therapy for rapidly growing vestibular schwannoma (VS)." (PMID 24594707, 2014). "On the other hand, there are reports that indicate involvement of Let-7a with constitutively active and phosphorylated STAT3 through NF-2 (neurofibromatosis-2)." (PMID 25539644, 2014). "Three out of 13 patients with NF2 had stigmata of neurofibromatosis (café-au-lait spots and Lisch nodules)." (PMID 22543431, 2012). "The peripheral cortical lamella wedge seen in this family is similar to that observed in Stickler syndrome and also with neurofibromatosis Type 2 (NF2)." (PMID 21850187, 2011). "It belongs to the family of phakomatoses and is subcategorized into two types: NF-1 (von Recklinghausen's disease) and NF-2 (bilateral acoustic neurofibromatosis)." (PMID 21569290, 2011). "Approximately 25% of neurofibromatosis type 2 (NF2) patients have been shown to be cases of mosaicism." (PMID 18433509, 2008). "In this study, we searched using the key terms “Neurofibromatosis Type 2,” “Type 2 Neurofibromatosis,” “acoustic neurofibromatoses,” “NF2,” and “neurofibromatosis” to identify full-text articles in Chinese and English detailing eye performance records of NF2 published from 1995 to 2022." (PMID 40852360, 2025). "To further investigate prognostic factors regarding PFS in PM, we analyzed 184 of those 1010 patients, who share the following common available covariates: Age, sex, EoR (subtotal resection, gross total resection), and neurofibromatosis status (NF2 or sporadic)." (PMID 39779595, 2025). "Particularly, eight studies examined populations with heterogeneous musculoskeletal pain (neck, head, limbs, shoulder and lumbar areas); one was focused on general chronic pain, one on Neurofibromatosis type 1 (NF1), and on Neurofibromatosis type 2 (NF2) or Schwannomatosis." (PMID 40150431, 2025). "However, it is ONLY as recent as the updated diagnostic criteria proposing the term “schwannomatosis” as an umbrella term for neurofibromatosis type 2 (NF2) and SWN, that novel classification of SWN based on disease-causing genes was proposed." (PMID 41247561, 2025). "NF2-SWN was initially thought to constitute a sub-form of neurofibromatosis." (PMID 41284083, 2025). "Our approach may be particularly appropriate for individuals with neurofibromatosis type 2 (NF2) and vestibular schwannomas (VS)." (PMID 39438593, 2024). "NF2 mutations associated with SP-EPN usually occur either as germline or mosaic mutations in patients with NF2-related schwannomatosis (NF2), previously known as neurofibromatosis type 2, or as somatic mutations in patients without NF2." (PMID 38265489, 2024). "Inactivating mutations in the NF2 gene, which codes for the tumor suppressor merlin, causes the autosomal-dominant tumor predisposition disorder of the nervous system NF2-related Schwannomatosis (NF2-SWN, formerly known as neurofibromatosis type 2)." (PMID 38945076, 2024). "Neurofibromatosis type 2 (NF2), also known as NF2-related schwannomatosis (SWN), is a rare dominantly inherited genetic disorder mainly characterized by the presence of vestibular schwannomas (VSs) in addition to a range of other tumors that affect both the central and peripheral nervous systems." (PMID 39618887, 2024). "Additionally, three heterogeneous disorders make up the definition of NF, which are neurofibromatosis type 1 (NF1), neurofibromatosis type 2 (NF2), and schwannomatosis." (PMID 37181996, 2023).
neurofibromatosis type 2 (continued). "Importantly, in a mouse model of neurofibromatosis type 2 (NF2), in which regeneration after a crush injury is strongly impaired, type IV collagen was found to be markedly increased post-injury compared to wildtype nerves." (PMID 37964793, 2023). "Multiple paraspinal schwannomas are typical of neurofibromatosis type 2 (NF2)." (PMID 37046591, 2023). "Most have previously been proposed as biomarkers in a specific tumor (or tumor-related condition): C15orf48 in esophageal cancer, NF2 in neurofibromatosis, CMTM6 in renal adenocarcinoma, PLEK2 in lung adenocarcinoma, RRM2 in glioma, HOXA1 in breast and gastric cancers, and SAA2 in renal cancer." (PMID 34204789, 2021). "The neurofibromatosis family of disorders may consist of up to eight related clinical entities, though the term is most often used to described three syndromes—neurofibromatosis type I (NF1), neurofibromatosis type II (NF2), and schwannomatosis." (PMID 31161239, 2020). "In conclusion, MPMNs may develop via the same mechanism as CNS meningiomas or neurofibromatosis syndrome, through deletion of the NF-2 gene." (PMID 30542514, 2018). "Merlin is a tumor suppressor protein, coded by the NF2 gene (Neurofibromatosis type II)." (PMID 26980710, 2016). "Mice heterozygous for NF2 develop a variety of cancers, including osteosarcomas, although neurofibromatosis 2 patients do not normally develop osteosarcomas, nor are mutations in NF2 frequently found in human osteosarcoma samples." (PMID 26510912, 2015). "Vestibular schwannomas are usually sporadic and unilateral (95%) but may be bilateral when associated with neurofibromatosis type 2 (NF2) syndrome, which is caused by germline mutations of the neurofibromin 2 (NF2) gene." (PMID 23354516, 2013). "Thirteen (18 %) patients had neurofibromatosis type 2 (NF2)." (PMID 22543431, 2012). "If there is a mutation in the NF2 gene, as in people with neurofibromatosis type 2, then a defective “merlin” (neurofibromin 2) protein is produced that does not have tumor suppressor activity, and NF2 tumors then occur." (PMID 20657692, 2010). "Germinal mutations in NF2 are responsible for type 2 neurofibromatosis, but NF2 patients are not prone to develop mesothelioma." (PMID 19523217, 2009). "Neurofibromatosis encompasses a spectrum of genetic disorders predisposing to tumor growth, with neurofibromatosis type 1 (NF1) occurring in approximately one in 3500 births and neurofibromatosis type 2 (NF2) and schwannomatosis in roughly one in 40,000 births." (PMID 39860457, 2025). "Neurofibromatosis type 2 is caused by mutation of neurofibromin 2 (NF2) gene mutation, a tumor suppressor gene with inhibitory roles in cell proliferation while the inherited loss of NF2 is not the cause of schwannomatosis." (PMID 39981185, 2025). "The term includes NF2-related schwannomatosis (NF2-SWN), previously known as neurofibromatosis type 2." (PMID 40510571, 2025). "Because mutations in human PI4KA and NF2 cause overlapping neurodevelopmental defects such as hypomyelination and cataracts, PI4KA-related disorders might be driven by defective Hippo signaling as occurs in Neurofibromatosis type II." (PMID 39116228, 2024). "Mutations in the SMARCB1 (otherwise known as INI1, BAF47, or hSNF5 gene and centromeric to the NF2 gene situated on chromosome 22) and LZTR1 genes (also located on chromosome 22, close to the former gene), which suppress tumors, are associated with this type of neurofibromatosis." (PMID 35053664, 2022).
neurofibromatosis type 2 (continued). "This may in part explain the lack of predisposition to developing cancer in patients with neurofibromatosis 2, though the explanation is not complete, since there remains considerable overlap between neurofibromatosis 2 and cancer-related NF2 aberrations." (PMID 24393766, 2014). "Neurofibromatosis type 1 (NF1) and NF2 -related Schwannomatosis ( NF2 -SWN) are both inherited syndromes characterized by Schwann cell tumors." (PMID 42125750, 2026). "Three types of neurofibromatosis have been recognized, namely, neurofibromatosis type 1 (NF1), neurofibromatosis type 2 (NF2), and schwannomatosis." (PMID 39211690, 2024). "Neurofibromatosis is a rare genetic and tumor-prone disorder affecting the nervous system, including NF1, NF2, and schwannomatosis." (PMID 39193326, 2024). "Schwannomatosis is part of the neurofibromatosis spectrum, along with NF1- and NF2-related conditions." (PMID 39062695, 2024). "These include peripheral nerve cancers (neurofibromatosis type 1 (NF1), neurofibromatosis type 2 (NF2), schwannomatosis, etc.)." (PMID 39007948, 2024). "The neurofibromatosis disease spectrum includes neurofibromatosis types 1 and 2 (NF1, NF2) and schwannomatosis (SWN)." (PMID 37301968, 2023). "Neurofibromatosis can be divided into 3 types: Neurofibromatosis type I (NF1), Neurofibromatosis type II (NF2) and schwannomatosis (SWN)." (PMID 37301968, 2023). "Based on clinical information (tumor types, café au lait spots), patients #12 and #13 were diagnosed with neurofibromatosis type 1 (NF1) and type 2 (NF2), respectively." (PMID 38139220, 2023). "Neurofibromatosis (NF; NF1, NF2) is a genetic, neurocutaneous disorder characterized by nerve sheath tumors of the central and peripheral nervous system, including the brain, spinal cord, and skin." (PMID 38127915, 2023). "STX3451 has been previously shown to be cytotoxic to cell lines of the rare neurofibromatosis NF1 and NF2 tumors." (PMID 35744942, 2022). "The neurofibromatosis syndromes, including NF1, NF2, and schwannomatosis, are tumor suppressor syndromes characterized by multiple nervous system tumors, particularly Schwann cell neoplasms." (PMID 34604034, 2021). "Neurofibromatosis (NF) is an autosomal genetic disorder with three types, including NF1, NF2, and schwannomatosis." (PMID 34430126, 2021). "According to the classification of the National Institute of Health (NIH) in 1988, neurofibromatosis comprises neurofibromatosis type 1 (NF1) and type 2 (NF2)." (PMID 33691671, 2021). "Somatic NF2 mutations have also been reported in a variety of cancers, but interestingly these mutations do not cause the same tumors that are common in hereditary neurofibromatosis 2, even though the same gene is involved and there is overlap in the site of mutations." (PMID 24393766, 2014). "Schwannomatosis or neurilemmomatosis are multiple schwannomas without other stigmata of neurofibromatosis NF-1 and NF-2." (PMID 40337438, 2025). "In neurofibromatosis type 2 (NF2), SRS offers durable tumor control, though hearing preservation and clinical outcomes varies as it contingent on the complex clinical presentation and disease burden, a unique challenge of NF2 patients." (PMID 41085808, 2025). "In our literature review, there are no case reports of cardiac myxoma in patients with neurofibromatosis type 2 (NF2)." (PMID 40713130, 2025). "Research has shown that cells lacking NF2 exhibit elevated oxidative stress, which promotes cancer development and the onset of diseases such as neurofibromatosis type 2." (PMID 39594616, 2024). "We present histopathological proof of the extremely rare bilateral occurrence of intracochlear schwannomas with negative blood genetic testing for neurofibromatosis type 2 (NF2)." (PMID 37904024, 2023). "Neurofibromatosis comprises neurofibromatosis type 1 (NF1) and type 2 (NF2)." (PMID 33691671, 2021).
neurofibromatosis type 2 (continued). "STS, soft tissue sarcomas; MRT, malignant rhabdoid tumor; CNS, central nervous system; MPNST, malignant peripheral nerve sheath tumor; NF-1, neurofibromatosis type 1; NF-2; neurofibromatosis type 2, GI, gastrointestinal; NA, data not available." (PMID 33796273, 2020). "An additional problem is that no specific code exists for NF1 in the International Classification of Diseases (ICD), so that it is not possible to distinguish it from other types of neurofibromatosis, such as neurofibromatosis type 2 (NF2)." (PMID 21439034, 2011). "However, only 10.3% of patients were diagnosed with a neurocutaneous disorder, and none had neurofibromatosis type 1 (NF1) or neurofibromatosis type 2 (NF2)." (PMID 40217683, 2025). "The Response Evaluation in Neurofibromatosis and Schwannomatosis (REiNS) International Collaboration's Patient‐Reported Outcomes (PRO) working group has systematically reviewed and published consensus guidelines for QoL endpoints in NF1, NF2, and schwannomatosis trials." (PMID 40510571, 2025). "Second, while a previous study revealed that QoL tended to be more deteriorated in patients with neurofibromatosis than in healthy subjects, we could not compare the levels of QoL between patients with NF2 and the general population." (PMID 39198186, 2024). "However, it is unlikely that the few NF2 individuals that might have been misclassified as NF1 have impacted the results, as NF2 overall constitutes only a fraction of all patients with neurofibromatosis." (PMID 37490289, 2023). "Patients were considered positive if those fields had mention of “NF1”, “Recklinghausen”, or “neurofibromatosis” (and various misspellings), unless the disease term was in close proximity to an exclusion word/phrase (e.g. “no sign of”, “screen for”, “not”, “unconfirmed”, “NF2”)." (PMID 36028856, 2022). "Even when the conditions were separated officially in 1987 (with separate localisation of the genes), NF2-SWN remained classified as a neurofibromatosis despite the tumours pathognomonic for NF1, neurofibromas, not being a feature of NF2-schwannomatosis." (PMID 41160189, 2025). "In a Japanese death certificate study, mean age at death from neurofibromatosis was 43 years, but NF1 and NF-2 were not clearly separated." (PMID 21542925, 2011).
Vestibular schwannoma (162 papers, 2006 to 2026). A vestibular schwannoma (also known as acoustic neuroma, acoustic neurinoma, or acoustic neurilemoma) is a benign, usually slow-growing tumor that develops from the VIIIth cranial nerve supplying the inner ear. "Rationale: NF2-related schwannomatosis (NF2-SWN) is a progressive neurological disorder with a hallmark of bilateral vestibular schwannomas (VSs), leading to irreversible hearing loss and reduced quality of life." (PMID 41695475, 2026). "This study explored the genetic causes of vestibular schwannomas in three groups: patients with NF2, younger patients with a unilateral tumor, and older patients with a unilateral tumor." (PMID 39941762, 2025). "In all three study groups, biallelic inactivation of the NF2 gene was the main cause of vestibular schwannoma tumorigenesis." (PMID 39941762, 2025). "In the present study, causative genetic alterations of vestibular schwannomas were investigated from patients with NF2, young patients with uVS (age ≤ 30 years), and older patients with uVS (age ≥ 40 years)." (PMID 39941762, 2025). "In the majority of cases, vestibular schwannoma is unilateral and solitary, but in 5% to 7%, it is associated with NF2." (PMID 39941762, 2025). "Specifically, patients should meet one of the following criteria: bilateral vestibular schwannomas, an identical NF2 pathogenic variant in 2 or more anatomically distinct NF2-related tumors, 2 major criteria, or 1 major and 2 minor criteria." (PMID 40713130, 2025). "NF2 is characterized by bilateral vestibular schwannomas and is caused by mutations in the NF2 gene." (PMID 40247846, 2025). "The aim of this study was to evaluate the causative genetic alterations of vestibular schwannomas in different patient groups, i.e., patients with confirmed NF2, young patients with uVS (≤30 years), and older patients with uVS (≥40 years)." (PMID 39941762, 2025). "While this highlights the genetic heterogeneity in the tumorigenesis of vestibular schwannomas, the detection rates of genetic variants in genes other than NF2 remain low and vary across studies." (PMID 39941762, 2025). "Classification systems provide a general estimate of tumor size but lack precision in evaluating therapy and monitoring growth in NF2-associated vestibular schwannomas (VS)." (PMID 39824854, 2025). "In recent years, 3D segmented volumetric analysis has become increasingly important in the monitoring and treatment surveillance of NF2-associated vestibular schwannoma." (PMID 39824854, 2025). "The presence of vestibular schwannomas causing progressive deafness and balance issues is a characteristic feature of NF2." (PMID 40821302, 2025). "In conclusion, this study highlights the potential role of immune activation and glial dysregulation in the pathogenesis of SNHL in NF2-associated vestibular schwannomas." (PMID 40895102, 2025). "This broader scope enhances the clarity and validity of our findings regarding measurement techniques for monitoring NF2-associated vestibular schwannomas." (PMID 39824854, 2025). "People with heterozygous NF2 mutations typically develop Schwann cell tumors, especially vestibular schwannoma, but the specific role of NF2 in human embryonic development is unclear." (PMID 39921490, 2025). "The early evaluation of tumor volume and growth behavior in NF2-associated vestibular schwannoma (VS) by regular, serial cranial magnetic resonance imaging (MRI) is indispensable." (PMID 39824854, 2025). "Germline mutations in NF2 lead to autosomal dominant neurofibromatosis type 2, commonly characterized by bilateral vestibular schwannomas, ependymomas, cranial meningiomas, and spinal nerve root schwannomas." (PMID 39796693, 2024). "This study included two patients with NF2, a condition associated with bilateral vestibular schwannomas." (PMID 38892753, 2024).